TNF (tumor necrosis factor)
Diseases named in the same sentence as TNF in open-access papers (continued):
Sharing a sentence is not in itself a finding about the gene and the disease.
endothelial dysfunction (continued). "S1P interacting with S1PR2 may also have a pro-atherosclerotic effect by promoting the inflammatory response of endothelial cells due to the increased expression of pro-inflammatory factors such as tumor necrosis factor α (TNF-α), interleukin 1 (IL-1), stimulating endothelial dysfunction." (PMID 36119733, 2022). "Recent studies suggested that targeting the TNF signal pathway might comprise a viable therapeutic strategy to reduce disease burden in ischaemic vascular disease progression, particularly endothelial dysfunction, chronic inflammation, and atherosclerotic plaque development." (PMID 34483919, 2021). "Moreover, Trichostatin A (TSA), an organic compound which selectively inhibits the class I and II HDAC, was found to suppress the transcription of TNF-α, the latter being a detrimental signature involved in the ET-1/NO system imbalance, endothelial dysfunction and atherosclerosis." (PMID 33988232, 2021). "Pro-inflammatory cytokines such as TNF-α, IL-6, IL-8, and IL-18 are essential inflammatory mediators, aggravating the inflammatory response and inducing the expression of adhesion molecules in endothelial cells and leukocytes (E-selectin, and P-selectin), which worsen endothelial dysfunction." (PMID 33917744, 2021). "Furthermore, the ROS-dependent phosphorylation of ERK5 by phosphokinase-C-ζ (PKCζ) and the activation of tumor necrosis factor α (TNFα)- mediated pathway induces the degradation of eNOS leading to the reduced production of NO concentration and in turn contributing further to endothelial dysfunction." (PMID 35127755, 2021). "Previous reports demonstrated that miR-149-5p could alleviate endothelial injury caused by oxidized low-density lipoprotein (ox-LDL) through inhibiting PAPP-A and reduce endothelial dysfunction induced by high glucose through decreasing TNF-α and ER stress marker expression." (PMID 33381550, 2020). "In addition, DHY attenuated TNF-α-induced endothelial dysfunction." (PMID 32933152, 2020). "Several studies have reported that curcumin supplementation suppresses inflammation by downregulation of the expression of pro-inflammatory cytokines, such as TNF-α and IL-623, which might contribute to its anti-inflammatory role in decreasing exercise-induced endothelial dysfunction." (PMID 31337199, 2019). "Because endothelial cells express CB1/CB2 receptors and CBs elicit anti-inflammatory defense facing cytokine-dependent endothelial dysfunction, we examined whether CBs could ameliorate the increase in Cx43 hemichannel activity evoked by IL-1β/TNF-α and high glucose in EAhy cells." (PMID 30158937, 2018). "Thus, we hypothesize that DMY attenuates TNF-α-induced endothelial dysfunction through mediating miR-21/DDAH1/ADMA cascade, which in turn results in enhancing NO production." (PMID 29682517, 2018). "Moreover, a feedback signaling may exist between SelS and NF-κB, and the overexpression of SelS attenuates TNF-α-induced endothelial dysfunction by inhibiting the p38 MAPK and NF-κB pathways in HUVECs." (PMID 29805311, 2018). "Therefore, we hypothesized that IL-6 is a critical contributor to coronary endothelial dysfunction in T2D and that the interaction between IL-6 and TNF-α exacerbates endothelial dysfunction." (PMID 29095915, 2017). "We hypothesized that VE-Cadherin might be involved in TNF-α-induced endothelial dysfunction." (PMID 28091531, 2017). "Here, we hypothesize that nicotine augments the CV effects of diet-induced obese rats via promoting macrophages to produce/release inflammatory cytokines such as TNFα, resulting in endothelial dysfunction via disrupting the balance between eNOS/NO and ROS in the vasculature." (PMID 29236702, 2017). "In turn, ICAM-1 and E-selectin participate in the regulation of inflammatory processes and may affect the pathology of endothelial dysfunction by activation of neutrophils and monocytes; their activity is also related to increased concentration of pro-inflammatory cytokines like TNF-α and MCP-1." (PMID 28959007, 2017).
endothelial dysfunction (continued). "Thus, inhaled silica particles could directly induce endothelial dysfunction by stimulating TNF-α expression and/or by increasing inflammatory cell recruitment in response to elevated secretion of pro-inflammatory cytokines." (PMID 27894297, 2016). "The hyper-inflammatory phase, which is initiated by tumor necrosis factor-α (TNFα) and subsequently amplified by interleukin-1 (IL-1) and IL-64, 10, may, together with downstream mediators, lead to endothelial dysfunction, characterized by vasodilation and increased permeability." (PMID 27653046, 2016). "Moreover, our studies suggest that CD40-driven secretion of TNF-α by HAEC may contribute to endothelial dysfunction during vascular inflammation." (PMID 26710229, 2015). "TNF-α may also show a key function in mediating endothelial dysfunction in erectile dysfunction." (PMID 25615941, 2015). "Another marker of endothelial dysfunction is the inability of acetylcholine to induce endothelium-dependent relaxation in vessel preparations in vitro and this was also induced by TNFα since it reduces endothelial nitric oxide synthase (eNOS) expression and activity." (PMID 26578976, 2015). "Dessein and Joffe reported significant reductions of IL-6 after 2 weeks of high-dose intra-articular methylprednisolone combined with DMARDs, associated with a decrease in markers of endothelial dysfunction, without significant changes in other inflammatory cytokines such as IL-1 and TNF-α." (PMID 24864133, 2014). "Interestingly, according to our findings, lack of association between flow-mediated endothelium-dependent vasodilatation and biomarkers of endothelial dysfunction was also observed in long-standing RA patients with active disease despite receiving periodical anti-TNF-alpha-infliximab therapy." (PMID 24864133, 2014). "Furthermore, NF-κB may induce tumor necrosis factor-α (TNF-α), which plays a pivotal role in endothelial dysfunction." (PMID 25009498, 2014). "In another study, reversal of endothelial dysfunction in patients with long-standing severe RA was only transient in response to TNF inhibitors, despite good control of systemic inflammation, suggesting that structural vascular changes might preclude more prolonged effects." (PMID 19344530, 2009). "Cytokines such as TNF-α, IL-6, IL-17A, CXCL9, CXCL10, and VCAM-1 are often elevated in both MASLD and SAH, playing crucial roles in immune cell recruitment, endothelial dysfunction, and fibrogenesis." (PMID 40977717, 2025). "First, spontaneous hypertensive rat models show reduced NO levels, elevated ET-1, inflammatory markers (e.g., IL-1β, TNF-α, MCP-1, VCAM-1), and ROS, indicating endothelial dysfunction, inflammation, and oxidative stress." (PMID 40230380, 2025). "For instance, adipose tissue in patients with SO secretes excessive proinflammatory cytokines, such as tumor necrosis factor-alpha (TNF-α) and interleukin-6 (IL-6), contributing to endothelial dysfunction and arterial stiffness." (PMID 40625352, 2025). "It is therefore not surprising that ADMA has been associated with endothelial dysfunction among multiple organ systems, cardiovascular and noncardiovascular, as its presence is associated with increased levels of inflammatory cytokines, including IL-1β, TNF-α, IL-6, IL-10, IL-4, IL-2, and more." (PMID 39941130, 2025). "The studies reviewed highlight a multifactorial process involving inflammatory agents such as CRP, S100 proteins, IL-18, IL-33, TNF, and osteopontin, alongside impaired HDL function, endothelial dysfunction, and altered immune cell profiles." (PMID 40943152, 2025). "Administering recombinant CST6 to endothelial cells enhanced markers of endothelial dysfunction and LGMN expression in the presence of TNFα." (PMID 40234537, 2025). "We confirmed successful induction of endothelial dysfunction by confirming the upregulation of VCAM1 (P = 0.0031 at 10 ng/mL TNFα), ET-1 (P = 0.0034 at 10 ng/mL TNFα) and ICAM1 (P = 0.0014 at 10 ng/mL TNFα)." (PMID 40234537, 2025).
endothelial dysfunction (continued). "During inflammation, levels of proinflammatory cytokines such as tumor necrosis factor (TNF)-α, interleukin (IL)-6, and IL-1β increase, which trigger apoptosis and fibrosis in cardiomyocytes and contribute to endothelial dysfunction, are increased." (PMID 40004844, 2025). "Recent evidence supports that periodontal inflammation contributes to systemic endothelial dysfunction and plaque instability through inflammatory mediators such as C-reactive protein (CRP), interleukin-6 (IL-6), and tumor necrosis factor-α (TNF-α)." (PMID 41303261, 2025). "Infection triggers a robust inflammatory response with high levels of cytokines like interleukin-6 (IL-6) and tumor necrosis factor-alpha (TNF-α), driving endothelial dysfunction and widespread tissue injury." (PMID 41158128, 2025). "To gain insights into the importance of NF‐κB signaling in endothelial dysfunction triggered by PRMT1 inhibition, we examined the nuclear localization of p65/NF‐κB in response to furamidine and TNF‐α treatment by immunostaining and nuclear fractionation." (PMID 40135804, 2025). "Additionally, the release of several cytokines in GBS (tumor necrosis factor-α, interleukin-6, interferon-γ, and IL-17) responsible for systemic immune activation, which, in our hypothesis, could lead to endothelial dysfunction and altered vascular permeability, is seen in PRES." (PMID 40988737, 2025). "Visceral adipose tissue secretes bioactive molecules such as tumor necrosis factor-α (TNF-α), interleukin-6 (IL-6), and angiotensinogen, which collectively promote vascular inflammation, endothelial dysfunction, and increased arterial stiffness." (PMID 40703406, 2025). "Its pathophysiology involves endothelial dysfunction, platelet activation, and proinflammatory cytokine networks, particularly those mediated by IFN and TNF, that promote vascular remodeling." (PMID 41458701, 2025). "Inflammatory cytokines like IL-1β, IL-6, and TNF-α are elevated following SAH, driving endothelial dysfunction and blood-brain barrier breakdown, which can worsen brain injury." (PMID 40783564, 2025). "Chronic inflammation, marked by elevated cytokines (e.g., IL-6, TNF-α) and acute-phase reactants like CRP, accelerates endothelial dysfunction and plaque instability." (PMID 41202086, 2025). "Elevated inflammatory markers, such as interleukin-6 (IL-6) and tumor necrosis factor-alpha (TNF-α), have been observed in patients with PAD, contributing to endothelial dysfunction and plaque formation." (PMID 40909223, 2025). "Elevated levels of pro-inflammatory cytokines such as interleukin-6 (IL-6) and tumor necrosis factor-alpha (TNF-α) are commonly observed in CKD patients, contributing to renal fibrosis and endothelial dysfunction." (PMID 40217935, 2025). "Another target for cytokine modulation is TNF-α, and anti-TNF-α agents, such as infliximab, are currently being explored as therapies for TBI, particularly for their ability to ameliorate endothelial dysfunction in the setting of TBI." (PMID 41050281, 2025). "The cytokine pattern observed in our oocyte-donation cohort—with increased IL-6, IL-1β, TNF-α, CXCL10, and VEGF—parallels these findings and supports the concept that immune activation and endothelial dysfunction are central to the disease process." (PMID 41561632, 2025). "This cascade stimulates the production of cytokines (e.g., IL-6, TNF-α), acute-phase proteins (e.g., CRP), and adhesion molecules, which collectively contribute to endothelial dysfunction and systemic inflammation." (PMID 40870942, 2025). "Of note, TNF-α has been shown to upregulate MCP-1 expression and secretion during the inflammatory process of endothelial dysfunction in pre-clinical studies of type 2 diabetes." (PMID 40843692, 2025). "Compared to IL-6 and TNF-α, which primarily indicate systemic inflammation, VCAM-1 is a more specific marker of endothelial dysfunction." (PMID 40385768, 2025).
endothelial dysfunction (continued). "Consistent with the expression of endothelial dysfunction markers, increased pro-inflammation markers (NLRP3 inflammasome, TNF-α, and NF-κB) induced by d-flow accompanied with decreased expression of eNOS and anti-inflammatory marker TGF-β induced by OSS." (PMID 38646649, 2024). "The obtained PCR results showed a significant decrease in TNF-α as inflammatory marker and TGF-β as the marker of endothelial dysfunction in treated group compared to the diabetic group." (PMID 39229583, 2024). "Long night periodical hypoxia episodes determine inflammation with oxidative stress and release of systemic inflammatory mediators like TNF-α, IL-6, IL-8, and CRP, which lead to endothelial dysfunction and atherosclerotic plaque formation." (PMID 39585008, 2024). "Prediabetes and hypertension induce endothelial dysfunction and inflammation by elevating ICAM-1, P-selectin, and TNF-α." (PMID 38397916, 2024). "In particular, in MetS, alterations in the levels of leptin, resistin, tumor necrosis factor-α (TNF-α), IL-6, angiotensin II, endothelin-1 (ET-1), and adiponectin lead to endothelial dysfunction and vasoconstriction." (PMID 38892574, 2024). "Elevated levels of advanced glycation end-products and pro-inflammatory cytokines like tumor necrosis factor-α and interleukin-6 in GDM further contribute to endothelial dysfunction and the development of PIH." (PMID 39356701, 2024). "Cytokines such as interleukin-6 (IL-6), tumor necrosis factor-alpha (TNF-alpha), and hormones such as adiponectin (adpN) can directly contribute to endothelial dysfunction by decreasing nitric oxide bioavailability and increasing pro-inflammatory adhesion." (PMID 38571360, 2024). "In the future, we will further explore the mechanism by which biochanin A can improve endothelial dysfunction by binding to its target proteins AKT1 and TNF-α, to provide theoretical support for the possibility of biochanin A as a clinical therapeutic drug." (PMID 38195507, 2024). "In step-flow chamber, d-flow markedly inhibited MerTK expression while induced endothelial dysfunction, indicating increased expression of pro-inflammatory signaling such as NLRP3 inflammasome (NLRP3, pro-IL-1β, and cleaved IL-1β), TNF-α, and NF-κB." (PMID 38646649, 2024). "We identified inflammatory and endothelial dysfunction markers (ADAMTS-13, TNF-α, GDF-15, MIP-1β, VEGFA, MPO, and MIC-1) that cooperate in a common pathway and are increased in FD patients’ plasma samples." (PMID 38892211, 2024). "To investigate the role of oleracones in mitigating endothelial dysfunction, we examined the effect of oleracones on HL-60 leukocyte adhesion to HBMVEC monolayers treated with TNF-α." (PMID 36768379, 2023). "Increased NC has also been correlated with increased markers of inflammation (interleukin 6 [IL-6], tumor necrosis factor-alpha [TNF-alpha], C3, C4) and endothelial dysfunctions (E-selectin)." (PMID 37123795, 2023). "Adipose tissue is an active endocrine organ that produces several pro-inflammatory cytokines, including interleukin-6 (IL-6) and tumor necrosis factor-alpha (TNF-α), which can promote endothelial dysfunction and vascular remodeling." (PMID 37416924, 2023). "Reactive oxygen species (ROS) of pro-inflammatory cytokines, such as interleukin 1 (IL1) and tumor necrosis factor (TNF)-a, are abnormally produced, and NO is released less frequently, resulting in endothelial dysfunction." (PMID 37887299, 2023). "Inflammatory cytokines, such as interleukin-1β (IL-1β), tumor necrosis factor-α (TNF-α), and C-reactive protein (CRP), promote endothelial dysfunction, leukocyte recruitment, and smooth muscle cell migration, proliferation, and apoptosis." (PMID 37298518, 2023). "Inhibition of miR-19b-3p reduced TNF-α and IL-1β expression levels in ox-LDL-HUVEC and AS mice and mitigated endothelial dysfunction." (PMID 37469665, 2023).
endothelial dysfunction (continued). "Endothelial dysfunction (expressed as FMD%) was correlated with focus score, ESSDAI, levels of anti-SSA and anti-SSB antibodies, beta-2 microglobulin, IL-6, and TNF-α, with statistical significance." (PMID 37762225, 2023). "The last group showed greater changes in biomarkers that induce endothelial dysfunction and inflammation, with an increase in the levels of inflammatory molecules and cytokines, which are expressed with a slight increase in ICAM-1 and TNF-a." (PMID 38162982, 2023). "In contrast, preeclampsia is characterized by a predominance of Th1 T-cells and pro-inflammatory cytokines such as tumor necrosis factor (TNF) and interferon-gamma, which likely contributes to abnormal placentation and subsequent endothelial dysfunction." (PMID 35925932, 2022). "PCOS per se has been viewed as a state of chronic low-grade inflammation with increased production of specific cytokines and chemokines such as TNFα, IL-1, IL-6, follistatin, CRP, and adhesion molecules involved in endothelial dysfunction." (PMID 35564864, 2022). "Consumption of a single high-fat meal rich in saturated fatty acids can induce endothelial dysfunction in otherwise healthy subjects, as evidenced by the related increased concentrations of VCAM-1, ICAM-1, IL-6, IL-18, and TNF-α." (PMID 35268723, 2022). "Evidence has shown that vascular cell adhesion molecule 1 (VCAM-1), tumor necrosis factor alpha (TNF-α), and VEGF-A are closely related to vascular lesions, especially VCAM-1, which is a biomarker of endothelial dysfunction." (PMID 36448064, 2022). "Some cytokines like tumor necrosis factor alpha (TNF-α) and interleukin-6 (IL-6) are also suggested to take part in the development of endothelial dysfunction and arteriosclerosis in GHD." (PMID 35106704, 2022). "Recently, it has been demonstrated that vascular inflammation secondary to elevated levels of proinflammatory cytokines, such as tumor necrosis factor alpha (TNF-α), plays a crucial role in endothelial dysfunction." (PMID 35206342, 2022). "Interaction between TNF-α and NF-kB signaling activates IKK-β and increases oxidative stress, resulting in endothelial dysfunction in type 2 diabetes." (PMID 34944525, 2021). "It is well-established that tumor necrosis factor-alpha (TNF-α), a major pleiotropic proinflammatory cytokine, plays a pivotal role in endothelial dysfunction and subsequent damage to vascular function." (PMID 34830366, 2021). "Adipokines such as leptin, adiponectin and resistin, cytokines, TNF-α, IL-1β, IL-6, IL-8, and MCP-1, and reactive oxygen and nitrogen species (ROS and RNS) affect endothelial dysfunction development through direct and indirect mechanisms." (PMID 33803343, 2021). "TNF-α inhibits nitric oxide synthase (NOS) activity in vascular endothelial cells, resulting in reduced NO-induced vasodilation, which leads to endothelial dysfunction and neurotrophic vascular damage and induces neuropathy." (PMID 34159207, 2021). "The effects of TNFα and IL1β blocking antibodies as well as FAK inhibitor on CAR-T therapy-induced endothelial dysfunction need to be verified in vivo." (PMID 34093519, 2021). "Interleukin (IL)-6, IL-8, and tumor necrosis factor (TNF)-α are usually elevated and are related to endothelial dysfunction and tubular injury." (PMID 32793191, 2020). "Patients with severe disease have been shown to have increased levels of IL-6, TNFα, MCP1, MIP1A, and IP10, which is also correlated with endothelial dysfunction and increased levels of D-dimer." (PMID 32760409, 2020). "On the other hand, TNF-α and IL-1 increase the binding of low density lipoproteins (LDL) to endothelium and smooth muscle, up-regulating the LDL receptor gene, inducing endothelial dysfunction and smooth muscle cell proliferation." (PMID 32388515, 2020).